IL18 (interleukin 18)
Diseases named in the same sentence as IL18 in open-access papers (continued):
Sharing a sentence is not in itself a finding about the gene and the disease.
psoriasis (continued). "Taking into account the fact that psoriasis is a Th1-type disease, IL-18 may be regarded to be ofsome importance in its pathogenesis." (PMID 17611614, 2007). "Therefore, the function of IL-18 in psoriasis development is likely important." (PMID 37883350, 2023). "We then used these variants as instrumental variables to estimate the causal effects of IL-18 levels on the risk of developing five common IMIDs: rheumatoid arthritis (RA), systemic lupus erythematosus (SLE), inflammatory bowel disease (IBD), ankylosing spondylitis (AS), and psoriasis." (PMID 38031150, 2023). "The IL-18/IL-18 receptor (R) α signaling pathway is important for Th1 cytokine production and differentiation of Th1 cells; however, its role in the pathogenesis of psoriasis remains unknown." (PMID 37964882, 2023). "Furthermore, it was concluded that ASC and IL-18 peripheral blood proteins can also be used clinically as inflammatory biomarkers for screening, disease prognosis and estimation of therapeutic response in psoriasis patients." (PMID 37325658, 2023). "We firstly found that the IMQ-induced psoriasis-related female mice showed depressive- and anxiety-like behaviors, which were associated with microglial activation, the up-regulation of NLRP3, Caspase-1, IL-18, and IL-1β, and the down-regulation of CRMP2 and α-tubulin." (PMID 36138986, 2022). "Overall, these data may indicate the potential role of IL-18 in psoriasis therapy." (PMID 36032110, 2022). "In conclusion, serum levels of TNF-α, IFN-γ, IL-2, IL-6, IL-8, IL-18, IL-22, chemerin, lipocalin-2, resistin, sE-selectin, fibrinogen and C3 were significantly elevated and serum level of adiponectin was significantly decreased in psoriasis patients compared to healthy individuals." (PMID 29416693, 2018). "Additionally, plasma IL-18 concentration is significantly related to the severity of psoriasis." (PMID 26901187, 2016). "In addition, serum IL-18 concentration and cutaneous IL-18 expression in the skin are significantly elevated in psoriasis patients compared with normal healthy donors, and there is a positive correlation between serum IL-18 expression and Psoriasis Area Severity Index (PASI)." (PMID 26901187, 2016). "IL-18 might be a marker of disease severity in psoriasis, AD, LE, or acute GVHD." (PMID 26690141, 2015). "Our cytokine analysis showed elevated levels of IL-6, IL-18, and IL-33, demonstrating a complex network of interactions in TNF inhibitor-induced psoriasis." (PMID 40678000, 2025). "A recent investigation discovered that the combination of recombinant mouse (rm) IL-18 with rmIL-23 exacerbates inflammation, upregulates IFN-γ and CXCL9, and enhances psoriasis-like epidermal hyperplasia." (PMID 39126010, 2024). "Whole blood from healthy volunteers or psoriasis patients was pretreated in vitro with JNJ-77242113, then stimulated with IL-23 in the presence of IL-2 and IL-18." (PMID 39080319, 2024). "Increased serum concentrations of the circulating inflammatory cytokines IL-2, IL-17, IL-18 and IFN-γ were significantly correlated with psoriasis." (PMID 37883350, 2023). "We review existing studies examining the role of psychological or psychosocial stress at the molecular level in AD and psoriasis, highlighting the role of the HPA axis and IL-18 in AD, CRH and BDNF in psoriasis, and cortisol levels in both." (PMID 35572606, 2022). "In GCF, individuals with psoriasis showed higher levels of S100A8, IL-18 and sE-selectin in comparison to healthy individuals, independent of periodontal status." (PMID 35454992, 2022). "Recent studies have proven that expression of IL-18 and ASC proteins were significantly elevated in the group of patients with diagnosed psoriasis in comparison to healthy controls." (PMID 34072753, 2021). "Cytokines have a very important role in the pathogenesis of psoriasis, especially those produced by Th1 cells (IFN-γ, IL-2, and TNF-α) and those produced by dendritic cells (IL-18, IL-20, TNF-α, and IL-23)." (PMID 29619128, 2018).
psoriasis (continued). "Compared with the controls, patients with psoriasis had significantly higher BDI scores, BMIs, and serum concentrations of total cholesterol, IL-6, and IL-18; they had significantly lower 25(OH)D3 concentrations." (PMID 30092066, 2018). "Various proinflammatory cytokines, including IL-18, IL-17, IL-12, and TNF-α, which are elevated in psoriatic lesional skin and have critical roles in the pathogenesis of psoriasis, have been identified and targeted for psoriasis treatment." (PMID 26901187, 2016). "Notably, genes such as Nlrp3, Casp1, Casp4, IL-1β, IL-18, and Stat1 had high degree values, indicative of their significant position in the PPI network and potential targets for FZHFZY treatment of psoriasis." (PMID 41383588, 2025). "Another recent meta-analysis, which summarized data from several small studies showed that among numerous inflammatory markers, elevated serum concentrations of the inflammatory cytokines IL-2, IL-17, IL-18, and IFN-γ are present in untreated psoriasis patients." (PMID 39775226, 2025). "A meta-analysis, including 57 studies conducted on 2838 psoriasis patients, concluded that increased serum levels of IL-2, IL-17, IL-18, and IFN-γ significantly correlated with psoriasis, highlighting their potential role as biomarkers for monitoring disease activity." (PMID 40699767, 2025). "Serum levels of IL-17, IL-2, IL-18, and IFN-γ were substantially correlated with psoriasis." (PMID 39459618, 2024). "In previous studies, serum or plasma IL-18 concentration has been correlated with the severity of psoriasis and the Psoriasis Area and Severity Index (PASI), and therefore, IL-18 may be considered a possible biomarker of psoriasis." (PMID 36742296, 2023). "Of these, IL-2 [SMD = 1.29 (95% CI: 0.61–1.97; P <0.001)], IL-17 [SMD = 0.71 (95% CI: 0.12–1.30; P = 0.018)], IL-18 [SMD = 1.27 (95% CI: 0.64–1.90; P <0.001)], and IFN-γ [SMD = 1.90 (95% CI: 1.27–2.52; P <0.001)] levels had significant correlations with psoriasis." (PMID 37883350, 2023). "IL-18 has also been found to be the initiator of the cytokine cascade, and the concentration of IL-18 in serum correlates with the severity index (PASI) of psoriasis." (PMID 37883350, 2023). "Overall, our meta-analysis suggests that circulating inflammatory cytokine IL-2, IL-17, IL-18 and IFN-γ levels may be potent biomarkers of psoriasis in patients." (PMID 37883350, 2023). "We have demonstrated that elevated IL-18 levels increase the risk of SLE and IBD but not RA, AS, or psoriasis." (PMID 38031150, 2023). "Recently, in a clinical trial using human recombinant IL-18 BP in RA and Psoriasis patients, therapeutic efficacy was not achieved." (PMID 36032110, 2022). "Here keratinocytes are recognised producers of IL-18 as of relevance in psoriasis, cutaneous lupus and chronic eczema, however a main source of IL-18BP in the skin organ are fibroblasts which are not known to secrete IL-18." (PMID 35003136, 2021). "Another group of researchers from China showed that the combination of PlxnB2 and its soluble ligand, CD100, stimulates the production of IL-1β and IL-18 by keratinocytes and activates the NLRP3 inflammasome and the NF-kB pathway during the course of psoriasis." (PMID 34072753, 2021). "According to our results, approximately 23% of IL-18 and E-selectin GCF levels could be explained by psoriasis in our models." (PMID 34685372, 2021). "In addition, we demonstrated that concentrations of IL-18 and sE-selectin in the GCF in moderate/severe psoriasis patients were upregulated and downregulated, with high standard deviations, respectively." (PMID 34685372, 2021). "Although no IL-18 therapeutics are currently licensed, IL-18BP therapy was examined in rheumatoid arthritis and psoriasis patients with positive tolerance and safety profiles." (PMID 33643264, 2021).
psoriasis (continued). "In addition, recent studies indicate that cutaneous and systemic high-level expression of proinflammatory cytokines, such as IL-1β, IL-6, IL-12, IL-18, and interferon-γ (IFN-γ), are typically detected in psoriasis patients." (PMID 26901187, 2016). "Furthermore, HMGB1 upregulates the expression of TLR2, TLR4, and RAGE in the skin lesion area of psoriasis and activates the inflammasome and NF-κB pathway in keratinocytes to promote IL-18 secretion, which would aggravate the condition of IMQ model psoriasis mice." (PMID 38255845, 2024). "Urate crystals activate the NLR family pyrin domain-containing three inflammasomes in macrophages, resulting in the production of active IL-1β and IL-18, and promote the production of TNF-α in monocytes, indicating that UA might increase the levels of inflammatory cytokines promoting psoriasis." (PMID 36902720, 2023). "Moreover, QL-1200186 significantly inhibited IL-12/IL-18-induced IFNγ production in vivo and alleviated IMQ-induced psoriasis-like skin inflammation in mice, which confirms the importance of these pathways in psoriasis." (PMID 37845748, 2023). "There were nominal positive associations between PRS of psoriasis and sgp130 (P = 0.02) and PRS of anxiety and IL-18 (P = 0.03), and nominal negative associations between PRS of anxiety and sIL-2R (P = 0.02) and PRS of educational attainment and sIL-2R (P = 0.03)." (PMID 35082268, 2022). "Additionally, serum levels of free and total IL-18 were significantly higher in patients with AOSD than healthy donors and control patients with other diseases, including rheumatoid arthritis (RA), systemic lupus erythematosus (SLE) and psoriasis." (PMID 34640417, 2021). "Many previous studies revealed that psoriasis is an inflammatory disease, and patients with this disease may have higher serum levels of cytokines, such as tumour necrosis factor (TNF)-α, interferon (IFN)-γ, (interleukin (IL)-6, IL-8, IL-12, IL-17 and IL-18." (PMID 34290604, 2021). "In conclusion, IL-18 and sE-selectin levels in the GCF could be promising biomarker for psoriasis." (PMID 34685372, 2021). "Therefore, although IL-18 is not specific to psoriasis nor the sole biomarker for the condition, its increased levels in serum of patients with psoriasis suggests that IL-18 may be useful in diagnosing, monitoring, and understanding the pathogenesis of psoriasis." (PMID 39126010, 2024). "In particular, serum levels of IL-17A were strongly correlated with IL-1α, IL-15, IFN-γ, IL-18, TNF-α, IL-12B, IL-17F, and IL-22 in psoriasis but not in healthy controls." (PMID 36118416, 2022). "Of considerable interest, the correlation matrix revealed a distinct cytokine panel where cytokines (IFN-γ, IL-18, TNF-α, IL-12B, IL-17A, IL-17F, and IL-22) were positively correlated with each other in psoriasis patients but not in healthy controls." (PMID 36118416, 2022). "While an ideal biomarker for psoriasis was not yet found, there is increasing evidence supporting a potential role of VEGF, TGF-β1, HBD-2, and IL-18 in evaluating disease severity." (PMID 29619128, 2018).
rheumatoid arthritis (92 papers, 2006 to 2026). A chronic, systemic autoimmune disorder characterized by inflammation in the synovial membranes and articular surfaces. "This study systematically analyzes the association between interleukin-18 (IL-18) gene polymorphisms and rheumatoid arthritis (RA) susceptibility." (PMID 38328001, 2024). "IL‐18 is implicated in the pathogenesis of rheumatoid arthritis, potentially influencing joint damage by regulating immune responses and inflammatory processes." (PMID 39188114, 2024). "The hallmark of rheumatoid arthritis is the inflammation that is mediated by the macrophages and monocytes that cause release of pro-inflammatory cytokines like interleukin-18." (PMID 31258598, 2019). "IL-18BP is a natural antagonist of pro-inflammatory IL-18 cytokine linked to autoimmune disorders like rheumatoid arthritis." (PMID 27649785, 2016). "The purinergic P2X7R is associated with activation and release of IL-1 and IL-18, which is strongly implicated in the multiple inflammatory pathways involved in the pathogenesis of rheumatoid arthritis (RA)." (PMID 25566266, 2014). "IL-18 is associated with several human diseases including rheumatoid arthritis, and inflammatory bowel disease." (PMID 25426283, 2014). "IL-18 is associated with multiple chronic inflammatory diseases, including atopic eczema, rheumatoid arthritis, systemic lupus erythematosus, and Sjogren’s syndrome." (PMID 24143230, 2013). "For example, high levels of IL-18 are found in the synovial fluid of rheumatoid arthritis patients, and alleviation of rheumatoid arthritis symptoms is associated with a decrease in IL-18 levels." (PMID 18818761, 2008). "The IL-18 may play a significant role in elevating the risk of cervical cancer among rheumatoid arthritis patients." (PMID 38263277, 2024). "As recently reviewed by Spel, several SNPs in the genes encoding NLRP3, NLRP1, IL-1β, and IL-18, which lead to increased expression levels, were connected to the development of rheumatoid arthritis, gout, ankylosing spondylitis, and juvenile idiopathic arthritis." (PMID 35629398, 2022). "IL-18 plays an important role in host innate and adaptive immune defense but its aberrant activities are also associated with inflammatory diseases such as rheumatoid arthritis and Crohn's disease." (PMID 28352119, 2017). "In addition, several polymorphisms within the IL-18 promoter gene have been associated with different inflammatory and autoimmune diseases such as rheumatoid arthritis, systemic lupus erythematosus and sub-acute sclerosing panencephalitis." (PMID 25426283, 2014). "Elevated levels of IL-6, IL-18, IFNγ, IL-17, IL-23, and TNFα have been found in the serum of patients with rheumatoid arthritis, as well as psoriatic arthritis." (PMID 40170117, 2025). "Alternatively, IL-18 binding protein (IL-18BP), used as a decoy receptor for IL-18, attenuated levels of IL-17A production in a rheumatoid arthritis model." (PMID 40777291, 2025). "Despite numerous reports showing the presence of elevated IL-18 in rheumatoid arthritis, it is important to mention that measured IL-18 levels do not necessarily reflect its biological activity." (PMID 37415987, 2023). "In opposition to other inflammatory diseases, such as Crohn’s disease or rheumatoid arthritis, data regarding IL-18 and IL-18BP in animal models are scarce." (PMID 35054124, 2022). "IL-18, together with IL-12, induces high levels of IFNγ production by T cells, and its expression correlates with disease activities of rheumatoid arthritis and Crohn’s disease." (PMID 35626130, 2022). "The levels of IL18 are significantly elevated in patients with gouty arthritis and rheumatoid arthritis." (PMID 36199146, 2022). "Pathway analysis revealed concordant trends across all studies with pathways related to cytokine-cytokine interaction, IL18 signaling, fluid shear stress and rheumatoid arthritis." (PMID 35145507, 2021).
rheumatoid arthritis (continued). "Interleukin (IL)-18 and IL-1β are potent pro-inflammatory cytokines that contribute to inflammatory conditions such as rheumatoid arthritis and Alzheimer’s disease." (PMID 33101286, 2020). "Evidence has been presented that IL-18 plays a prominent role in the onset and maintenance of an inflammatory response during rheumatoid arthritis." (PMID 31861496, 2019). "Interleukin-18 gene shows down regulation in rheumatoid arthritis patients on disease modifying anti-rheumatic drugs therapy." (PMID 31258598, 2019). "IL-18 was also suggested to be involved in rheumatoid arthritis, as IL-18 mRNA and protein were present in rheumatoid synovial tissue at higher levels than in osteoarthritis." (PMID 31861496, 2019). "Expression analysis for interleukin-18 showed down regulation of gene in rheumatoid arthritis patients as compared to controls." (PMID 31258598, 2019). "The aim of this study was to analyze the gene expression of interleukin-18 in rheumatoid arthritis patients on disease modifying anti-rheumatic drug therapy." (PMID 31258598, 2019). "In patients with rheumatoid arthritis, active caspase 1 cleaved IL-1β precursors and IL-18 precursors to IL-1β and IL-18 to induce inflammation, respectively." (PMID 31367484, 2019). "In addition, it is known that patients with rheumatoid arthritis (RA) are more sensitive in their NO production system via iNOS and interleukin (IL)-18, and are reportedly more susceptible to NSAID-induced GI injuries when compared with other NSAID users." (PMID 31600995, 2019). "IL-18 also contributes to secondary progressive multiple sclerosis and rheumatoid arthritis joint inflammation, stimulating leukocyte chemotaxis, angiogenesis and cartilage destruction." (PMID 30072988, 2018). "IL-18 gene (-137G/C) promoter polymorphism has been associated with susceptibility to several diseases like CAD, Type 1 diabetes, rheumatoid arthritis, sarcoidosis, atopic eczema, adult-onset Still’s disease, and seasonal allergic rhinitis." (PMID 25822970, 2015). "In pathologies such as rheumatoid arthritis, IL-18 has been shown to promote migration, adhesion and activation of leucocytes through the release of different factors such as SDF1/CXCL12 and VCAM1/ICAM1." (PMID 24778454, 2014). "It has been elucidated that IL-18 along with IL-12 is a potent inducer of the inflammatory mediators by T lymphocytes, causing severe inflammatory disorders in autoimmune diseases such as rheumatoid arthritis (RA)." (PMID 22312407, 2012). "IL-18 plays important roles in the pathogenesis of inflammatory diseases such as atopic dermatitis, rheumatoid arthritis (RA), adult-onset Still's disease, Sjögren's syndrome, and inflammatory bowel diseases including Crohn's disease [see review]." (PMID 21915293, 2011). "In humans, IL-18 over-expression has been reported in rheumatoid arthritis, sarcoidosis, adult-onset Still's disease, vasculitis, lupus, urticaria and histiocytosis." (PMID 18818761, 2008). "Additionally, similar to other forms of rheumatoid nodules, higher levels of IL-1, together with IL-12, IL-18, IL-15, and IL-10, have been reported in pulmonary rheumatoid nodules." (PMID 37238933, 2023). "The cytokine IL-18 was selected from the rheumatoid arthritis pathway for validation." (PMID 36901727, 2023). "The production and function of IL-18 was also examined in patients with rheumatoid arthritis." (PMID 37415987, 2023). "Indeed, serum levels of free IL-18 were significantly higher in AOSD than in healthy subjects as well as in patients with active rheumatoid arthritis, systemic lupus erythematosus, ankylosing spondylitis, and psoriatic arthritis." (PMID 35054124, 2022). "On a side note, the priming or enhancement effect of IL-18 on ROS generation in neutrophils has also been shown in settings of bacterial infections, anti-neutrophil cytoplasm autoantibody (ANCA)-associated vasculitis, and rheumatoid arthritis." (PMID 33919154, 2021).